SHANK3 (SH3 and multiple ankyrin repeat domains 3)
Diseases named in the same sentence as SHANK3 in open-access papers (continued):
Sharing a sentence is not in itself a finding about the gene and the disease.
epilepsy (25 papers, 2010 to 2025). A brain disorder characterized by episodes of abnormally increased neuronal discharge resulting in transient episodes of sensory or motor neurological dysfunction, or psychic dysfunction. "Lavanya reported that the highest incidence of epilepsy was observed in patients with SHANK3 point mutations and deletions > 4 Mb." (PMID 40922359, 2025). "SHANK1, SHANK2, and SHANK3 variants have been associated with the development of ASDs, but they are also increasingly recognized as contributing to epilepsy, particularly through their role in synaptic excitability and plasticity." (PMID 39596051, 2024). "For example, SHANK3 variants are generally associated with more severe forms of epilepsy and cognitive impairment, while SHANK1 variants are linked to milder neurodevelopmental and epileptic presentations." (PMID 39596051, 2024). "In humans, SHANK3 mutations increase the likelihood of epilepsy and of atypical absence seizures in particular." (PMID 38002499, 2023). "Mutations in Shank3 have been implicated in the functional integrity of dendritic spines, and therefore SHANK3 haploinsufficiency can cause epilepsy risk due to abnormalities in the glutamatergic synaptic structure and function." (PMID 36142719, 2022). "Since some patients with PMDS or SHANK3-associated ASD suffer from epilepsy, it is of interest that such a phenotype has only been observed rarely in SHANK3-deficient mice." (PMID 34784886, 2021). "Our EEG findings contrast to some degree with the clinical picture of patients with SHANK3 mutations, as some patients with loss of function SHANK3 mutations have epilepsy and 67% have some EEG abnormality." (PMID 28638591, 2017). "A prospective natural history study of EEG and epilepsy in individuals with SHANK3 mutations will help determine to what degree the EEG abnormalities we observed in this mouse model relate to the clinical population." (PMID 28638591, 2017). "Molecular defects in synaptic structure and function in both ASD and epilepsy involve key proteins such as neuroligins and neurexins, critical for synapse alignment and activation, along with the scaffolding protein SHANK3." (PMID 38254951, 2023). "Molecular defects of SHANK3 underlie several neurodevelopmental entities, in particular ASD and epilepsy, whereas there is a paucity of data on the disease associations of SHANK1 and SHANK2." (PMID 36142719, 2022). "Molecular abnormalities in synaptic structures and functions in ASD and epilepsy frequently involve neuroligins and neurexins, proteins that are crucial for aligning and activating synapses along with the SHANK3 scaffolding protein." (PMID 36292706, 2022). "In addition, more than 100 disease genes have been described as related to ASD, including SHANK3, CNTNAP2 and NLGN4X, and many of them are also implicated in epilepsy." (PMID 36292706, 2022). "Yet, independent of the specific mechanism, our data raise prospects for some patients with SHANK3 mutations to also have a mild or absent epilepsy phenotype." (PMID 28638591, 2017). "DNAJC5, FRRS1L, SHANK3, SYN1, and SYN2 were epilepsy-related genes." (PMID 33584793, 2020). "In a case series of six Italian patients with 22q13.3 deletion syndrome, 3/6 had epilepsy (though one with a history of meningitis), 1/6 carried a deletion that did not involve SHANK3, and all 6 had a “benign course” as described by the authors." (PMID 32546186, 2020).
cognitive deficits (23 papers, 2012 to 2025). "Genetic studies support a link between Tau and Shank3, showing that Shank3 deficiency synergizes with Tau pathology to exacerbate synaptic and cognitive deficits." (PMID 41226815, 2025). "The degree of related mutations and cognitive impairment between SHANK1-3 also differs: patients with SHANK3 mutations suffer more cognitive impairment than those with SHANK1 or SHANK2 mutations." (PMID 36846568, 2023). "Such a demonstrated allelic dose–response effect is unique among all synaptic proteins and argues for a key role of Shank3 in synaptic pathologies underlying cognitive impairment." (PMID 37253603, 2023). "Although SHANK1 and SHANK2 mutations are also associated with ASD, cognitive deficits are more severe in patients with SHANK3 mutations." (PMID 34784886, 2021). "Individuals harboring different SHANK3 mutations display considerable heterogeneity in their cognitive impairment, likely due to the high SHANK3 transcriptional diversity." (PMID 25997006, 2015). "The phenotype of SHANK3 deficiency has been described primarily from case studies, with limited evaluation of behavioral and cognitive deficits." (PMID 23758760, 2013). "Reduced H3K4me2 methylation has been causally linked to the emergence of behavioral and cognitive deficits in other preclinical mouse models relevant to psychiatric and neurodevelopmental disorders, including models that are based on genetic deficiency of Shank3, Setd1a, and Kmt2c." (PMID 40102613, 2025). "The results of this study in human brain samples and in transgenic mice are consistent with the hypothesis that Shank3 deficiency makes a key contribution to cognitive impairment in AD." (PMID 37253603, 2023). "In addition, patients with SHANK3 mutations have severe cognitive deficits." (PMID 36846568, 2023). "Shank3 expression is reduced in aged and AD human brains along with a general trend of synaptic loss, which might be related to impaired glutamatergic neurotransmission, cerebral hypometabolism, and cognitive deficits." (PMID 34504419, 2021). "Surprisingly, our analysis revealed that the deletion of a single Shank3 allele in PV neurons was sufficient to induce behavioral changes, which contrasts with the absence of cognitive deficits in Shank3 full KO mice in heterozygosity." (PMID 37528484, 2023). "Autistic individuals with LoF variants in the four moderate-risk genes (NAV3, ITSN1, SCAF1 and HNRNPUL2; n = 95) have less cognitive impairment than 129 autistic individuals with LoF variants in highly penetrant genes (CHD8, SCN2A, ADNP, FOXP1 and SHANK3) (59% vs 88%, P = 1.9 × 10−6)." (PMID 35982159, 2022). "The model of Shank3-mutant mice has exhibited molecular impairments in the cortex and hippocampus neurons, causing deficits in the NMDA receptor-mediated neurotransmission associated with cognitive deficits." (PMID 35401120, 2022). "Furthermore, the degree of cognitive impairment in ASD may be due to mutations in the SHANK family members, the most significant being SHANK3." (PMID 36846568, 2023). "In this study, we investigated the relationship between Shank3 deficiency, cognitive impairment, as well as Aβ and tau neuropathologies in brain samples from the Religious Orders Study and in hemizygous 3xTg-AD mice lacking one Shank3 allele (Shank3Δex4-9), assessed at different ages." (PMID 37253603, 2023). "In turn, Shank3 knockout mice completely lack structural synaptic plasticity, which might at least in part explain the rigidity of behaviors, problems in adjusting to new situations and cognitive deficits seen in ASDs." (PMID 35682760, 2022). "In addition, many Shank3 mutations have been identified in ASD patients with severe cognitive deficits who do not have PMS." (PMID 35328799, 2022). "Haploinsufficiency of SHANK3 may be contributed to the development delay and cognitive impairment." (PMID 27099631, 2016).
cognitive deficits (continued). "Our data show the lack of structural synaptic plasticity in Shank3 knockout mice that might explain at least in part the rigidity of behaviors, problems in adjusting to new situations and cognitive deficits seen in ASDs." (PMID 35682760, 2022). "However, SHANK3-reexpression in these cells did not influence increased repetitive behaviors or cognitive deficits." (PMID 34784886, 2021).
bipolar disorder (22 papers, 2013 to 2025). A disorder of the brain that causes unusual shifts in mood, energy, activity levels and the ability to carry out day-to-day tasks. "SHANK3 variants are also known to be associated with an increased risk for regression, as well as for psychiatric disorders, including bipolar disorder and catatonia." (PMID 32050889, 2020). "Shank3, a protein located in the post-synaptic density, is linked to bipolar disorder’s pathophysiology and has been investigated in the context of ketamine’s antidepressant effects on individuals with bipolar depression." (PMID 40927563, 2025). "Therefore, both deletions and duplications of SHANK3 could be associated with bipolar disorder by disturbing neuronal homeostasis." (PMID 26572867, 2015). "In addition, recent reports of psychiatric comorbidity in individuals with SHANK3 deficiency suggest that, as patients age, they may be at increased risk for bipolar disorder." (PMID 23758760, 2013). "Lentivirus-mediated overexpression of miR-504, which mimics its reported expression change in postmortem brain tissues of bipolar disorder, decreased endogenous Shank3 protein in cultured hippocampal neurons." (PMID 26572867, 2015). "A variety of SHANK3 SNPs, including rs9616915, were analyzed, but none were found to be significantly associated with bipolar disorder." (PMID 34188957, 2021). "Neurobehavioral decompensation, including bipolar disorder, catatonia, and loss of skills, was observed in cases with PMS regardless of the underlying genetic defect, consistent with a role of SHANK3 in the psychopathological phenotype emerging as patients age." (PMID 31879555, 2019). "Our finding of clinical efficacy of lithium is in line with the recent idea that SHANK3 patients with ASD may present an atypical form of bipolar disorders." (PMID 25947967, 2015). "Together, these results suggest that the increased expression of miR-504 observed in postmortem brains of bipolar disorder and in a rat model of depression, might possibly lead to a decrease in Shank3 protein in some brain regions." (PMID 26572867, 2015). "Indeed, deletions of SHANK3 gene have been identified in some patients diagnosed with bipolar disorder." (PMID 26572867, 2015). "It is tempting to speculate that increased expression of miR-504 in the prefrontal cortex of bipolar disorder might contribute to pathogenesis, at least partly, by downregulating SHANK3 expression and dendritic spines as we demonstrated in the cultured hippocampal neurons." (PMID 26572867, 2015). "Specifically, we previously identified two SHANK3 duplication patients who presented with hyperkinetic disorders, such as attention deficit hyperactivity disorder (ADHD) and bipolar disorder, and early-onset generalized tonic-clonic seizures." (PMID 30305163, 2018).
fragile X syndrome (13 papers, 2011 to 2025). A genetic syndrome caused by mutations in the FMR1 gene which is responsible for the expression of the fragile X mental retardation 1 protein. "IPSCs have been used as disease models for Fragile X syndrome and Rett syndrome, and iPSCs have been generated from patents with deletions in SHANK3 which are implicated in a number of neurodevelopmental disorders." (PMID 28702161, 2017). "Numerous studies have indicated that synaptic-associated gene mutations may cause ASD, including fragile X mental retardation 1 (FMR1) (Fragile X syndrome), tuberous sclerosis gene (TSC) (tuberous sclerosis), SH3, and multiple ankyrin repeat domains 3 (SHANK3) [Phelan–McDermid syndrome (PMS)]." (PMID 35401120, 2022). "In Fmr1-knockout (KO) mice—a model for fragile X syndrome—the protein levels of several FMRP targets are increased in PSD fractions either from the neocortex or hippocampus, including Sapap1–3, Shank1, Shank3, and various glutamate receptor subunits." (PMID 36497075, 2022).
Rett syndrome (13 papers, 2014 to 2025). A severe neurodevelopmental disorder affecting the central nervous system.
Zinc deficiency (11 papers, 2014 to 2025). A deficiency of the essential metal Zinc; an essential cofactor for many enzymes. "At synapses in the CNS, for example, we have previously shown that SHANK2 and SHANK3 are regulated by zinc at developing synapses and lost from synapses in offspring of mice born from mothers with zinc deficiency." (PMID 35682762, 2022). "In line with this, we have previously observed a decrease of synaptic SHANK2 and SHANK3 by direct induction of zinc deficiency both in vitro and in vivo." (PMID 34741005, 2021). "Given that Shank3 levels both in vitro and in vivo regulate zinc transporter expression, a possible explanation for high incidence rates of zinc deficiency in PMDS can be found." (PMID 29875651, 2018). "In line with the described findings obtained from in vitro experiments, prenatal zinc deficiency in mice was found to tremendously affect synaptic Shank3." (PMID 29875651, 2018). "Intriguingly, a similar reduction in Shank3 protein levels was also observed in animals exposed to a mild zinc deficiency during their embryonic development and in primary hippocampal neurons cultured under zinc deficient conditions." (PMID 29875651, 2018). "While zinc deficiency depletes synaptic pools of Shank3, increased zinc levels were shown to promote synaptic scaffold formation." (PMID 29875651, 2018). "The loss of the zinc-sensitive SHANK proteins SHANK2 and SHANK3, notwithstanding whether caused directly by zinc deficiency or indirectly, may affect synapse function with possibly lasting effects on brain function later in life." (PMID 34741005, 2021). "Moreover, future studies on human individuals with either SHANK3 loss or early life exposure to zinc deficiency might now seek for similar alterations as we have seen them in the corresponding animal models." (PMID 30853900, 2019). "In vivo, loss of synaptic Shank family members during embryonic development through zinc deficiency was accompanied by ASD-like behavior later in life, and Shank2 and Shank3 knockout (KO) mice are well-studied ASD mouse models." (PMID 34741005, 2021). "Since a Shank3 deficiency may cause ASD, it is reasonable to infer that a synaptic zinc deficiency, which may cause a defect in Shank3 polymerization, might also contribute to synaptic dysfunction in ASD." (PMID 25182223, 2014). "Furthermore, it has been suggested that zinc signaling through Shank2 and Shank3 controls the AMPA receptor subunit switch in developing neurons, and that zinc deficiency may impair synaptic maturation and circuit formation that underlie ASD etiology." (PMID 33374671, 2020).
Alzheimer disease (9 papers, 2017 to 2025). A progressive, neurodegenerative disease characterized by loss of function and death of nerve cells in several areas of the brain leading to loss of cognitive function such as memory and language. "It has been reported that the splicing of the APP, APOE, SNCA, MAPT, DAO, SHANK3, and CACNA1C genes, which are recorded in the PsyGeNET database, were abnormal in patients with neurological diseases such as Parkinson’s disease, Alzheimer’s disease, and amyotrophic lateral sclerosis." (PMID 39858933, 2025).
attention deficit-hyperactivity disorder (7 papers, 2014 to 2019). A disorder characterized by a marked pattern of inattention and/or hyperactivity-impulsivity that is inconsistent with developmental level and clearly interferes with functioning in at least two settings (e.g. at home and at school). "Moreover, duplications of the SHANK3 gene have also been identified in patients with Asperger’s syndrome, BD, SCZ, and attention deficit hyperactivity disorder (ADHD)." (PMID 28469556, 2017).
depression (7 papers, 2015 to 2026). "In addition to SCZ and BD, “depressive disorders”, “alcohol use disorders”, and “cocaine use disorders” gene sets were significantly represented by the genes up-regulated in the Shank3 TG striatum." (PMID 28701918, 2017). "In this study, we compared LFP signals from the dmPFC and BLA during an SI test among wild-type mice, Shank3 KO mice as a model of ASD, and socially defeated mice as a model of depression." (PMID 35580019, 2022). "Our results indicating normal interactions between SHANK3 and Homer1 in Dlgap1 KO mice is consistent with the absence of any depression-related phenotype in these mice, including lack of effects in the FST and sucrose preference test." (PMID 29396406, 2018).
Asperger syndrome (6 papers, 2009 to 2018). "Nevertheless, it cannot be excluded that a general dysregulation of SHANK gene expression contributes to ASD pathology, as SHANK3 gene duplications have also been identified in individuals with Asperger syndrome." (PMID 30319350, 2018). "In the French family, the elder brother carrying the SHANK3 duplication was diagnosed with Asperger syndrome." (PMID 25188300, 2014). "Interestingly, overexpression of SHANK3 may also result in an ASD as evidenced by reports of Asperger syndrome in an individual with three copies of the SHANK3 locus." (PMID 21167025, 2010).
cognitive decline (5 papers, 2017 to 2025). "Another example is SHANK3, which is correlated with synaptic loss and cognitive decline." (PMID 40797190, 2025).
Timothy syndrome (5 papers, 2014 to 2021). "Similar abnormalities have been found in models of TSC, Timothy syndrome (TS), Phelan–McDermid syndrome (PMS) (SHANK3 mutations), and neuroligin and neurexin mutant mice." (PMID 29713304, 2018).
tuberous sclerosis (5 papers, 2013 to 2025). Hereditary disease characterized by seizures, intellectual disability, developmental delay, and skin and ocular lesions. "Commonly used models are often based on single-gene disorders associated with ASD, such as Tuberous Sclerosis (TSC) and Fragile X syndrome, or high-effect risk genes like SHANK3, NLGN3, and NLGN4, as they offer high construct validity and thereby increase relevance." (PMID 40611277, 2025).
22q11.2 deletion syndrome (4 papers, 2014 to 2024). 22q11.2 deletion syndrome (DS) is a chromosomal anomaly which causes a congenital malformation disorder whose common features include cardiac defects, palatal anomalies, facial dysmorphism, developmental delay and immune deficiency. "A 22q11.21 microdeletion encompassing the TBX1, SHANK3, SOX10, AP1B1, FBXO7, MYH9, and SPECC1L genes cause DiGeorge syndrome, which is associated with DD, ID, seizure, and cardiac malformations, with a prevalence of 1 in 4000." (PMID 37189911, 2023).